MIF (macrophage migration inhibitory factor)
Diseases named in the same sentence as MIF in open-access papers (continued):
Sharing a sentence is not in itself a finding about the gene and the disease.
atherosclerosis (continued). "Crucially, we demonstrate that secretory VSMCs act as key microenvironmental regulators, driving M1 polarization via MIF secretion and CD74 activation, potentially amplifying inflammatory cascades in atherosclerosis." (PMID 41383630, 2025). "Macrophage migration inhibitory factor (MIF) is a key mediator of many inflammatory diseases such as septic shock, rheumatoid arthritis, atherosclerosis and multiple sclerosis." (PMID 40421032, 2025). "MIF binds to the chemokines CXCR2 and CXCR4, recruits leukocytes, and accelerates the process of atherosclerosis." (PMID 38625586, 2024). "MIF has a chemokine-like function that activates CXCR2 and CXCR4, and thus can recruit monocytes and T lymphocytes to promote atherosclerosis." (PMID 36712241, 2022). "Anti-C5 did, however, reduce the development of atherosclerosis, limiting the total lesion size and severity independently of an effect on plasma cholesterol but with reductions in oxidized LDL (oxLDL) and macrophage migration inhibitory factor (MIF)." (PMID 36142647, 2022). "First, CD74 participates in T-cell antigen presentation independently of MIF and MIF2, and T-cells play an important role in atherosclerosis." (PMID 36712241, 2022). "Monocyte arrest elicited by MIF depends on CD74 and the complex formed by MIF/CXCR2 or MIF/CXCR4 in the context of inflammation and atherosclerosis." (PMID 33776775, 2021). "The specific targeting of the interaction between the atypical chemokine MIF and its receptor CXCR2, and its atherosclerosis‐promoting activity in a tailored peptide‐based approach is illustrated." (PMID 33125165, 2021). "Macrophage migration inhibitory factor (MIF) is an inflammatory cytokine and atypical chemokine with a key role in inflammatory diseases including atherosclerosis." (PMID 33125165, 2021). "In support of this, an antimalarial drug, artesunate, downregulated IFN induced STAT1 phosphorylation in SLE PBMC's in vitro, which reduced production of macrophage migration inhibitory factor (MIF), a key regulator of both atherosclerosis and SLE." (PMID 33640328, 2021). "MIF can be expressed at low levels in vascular smooth muscle cells and vascular endothelial cells, but when atherosclerotic plaques occur in the blood vessels, the production of MIF increases rapidly, suggesting it may be involved in the occurrence of atherosclerosis." (PMID 32560699, 2020). "We demonstrated that MIF is a functional ligand of chemokinereceptors CD74 and CXCR4 and that it participates in the regulation of monocyterecruitment in atherosclerosis promoted by P.gingivalis infection." (PMID 30506423, 2019). "In view of the CXCR4 protein in atherosclerosis, the function and expression of two alternative ligands of CXCR4, MIF and CXCL12 were summarized and compared." (PMID 31004184, 2019). "Macrophage migration inhibitory factor (MIF) is a multifunctional cytokine and critically affects atherosclerosis pathogenesis." (PMID 29482504, 2018). "In conclusion, endothelial MIF and KLF2 play a critical role in the initiation and progression of atherosclerosis." (PMID 29403061, 2018). "Macrophage migration inhibitory factor (MIF) is known to be a proinflammatory factor in many diseases, including atherosclerosis and rheumatoid arthritis." (PMID 27955690, 2016). "Subsequently, the role of two important inflammatory mediators that recently have been connected with CVD and atherosclerosis will be discussed and put into clinical perspective, namely the chemokines CXCL12 and macrophage migration-inhibitory factor (MIF)." (PMID 26257740, 2015). "The macrophage migration inhibitory factor (MIF) is a cytokine involved in the pathogenesis of RA and atherosclerosis." (PMID 22927710, 2012). "Our previous research elucidated the role of miR-19a-3p in atherosclerosis through the miR-19a/HBP1/MIF pathway upon that foundation, the current study aimed to investigate the expression levels of HOTAIR in both the plasma of atherosclerosis patients and foam cells." (PMID 38250607, 2024).
atherosclerosis (continued). "Furthermore, literature searches revealed various other studies that focused on the amelioration of atherosclerosis and related disorders by disrupting chemokine signaling, which focused for example on CX3CR1, MIF, CXCR3, and the CCL5-CXCL4 heterodimer." (PMID 34501271, 2021). "Aortas from these mice, when transplanted into apolipoprotein E (ApoE)−/− mice fed a high-fat diet, fail to express CCL2 and MIF and do not develop atherosclerosis, in contrast to the florid lesions seen in control WT aortas." (PMID 33458623, 2021). "There is evidence about the participation of MIF in atherosclerosis and ACS, but there is not much knowledge about MIF mRNA expression in ACS and specifically how this expression is changing between the clinical manifestations." (PMID 30057807, 2018). "Macrophage migration inhibitory factor (MIF) is a non-canonical cytokine that is involved in multiple inflammatory diseases, including atherosclerosis." (PMID 29403061, 2018). "Of particular interest, pathway enrichment analysis of the 34 common gene associated DMRs revealed epigenetic impairment of NRF2 oxidative stress (SOD2), DNA repair (BRCA1), thioredoxin (TXNRD1) and inflammatory pathways (MIF, PLA2G4D) in atherosclerosis conditions." (PMID 28698603, 2017). "Thus there is a forward feedback loop during atherosclerosis: TNF-α stimulates the expression of miR-19a to suppress HBP1 and subsequently elevate MIF production, which in turn increases TNF-α secretion." (PMID 28935967, 2017). "Besides the already described chemokines involved in atherosclerosis, in the recent years, more and more research has been focusing on two yet undiscussed chemokines, being CXCL12 and MIF." (PMID 26257740, 2015). "MIF has been recognized as an important CLF chemokine mediating leukocyte recruitment and arrest in the context of many inflammatory diseases, in particular atherosclerosis." (PMID 23720662, 2013). "In the context of atherosclerosis, interference with MIF binding to both CXCR2 and CXCR4 by using a MIF blocking antibody interfered with MIF’s pro-atherosclerotic functions, while it would leave the protective homeostatic functions of the CXCL12-CXCR4 axis preserved." (PMID 23720662, 2013). "Interestingly, an atherosclerosis animal model study 34 demonstrated that cholesterol feeding significantly increased MIF levels in New Zealand white rabbits, whereas those fed a normal diet did not exhibit elevated MIF levels." (PMID 41355948, 2026). "Together, MIF is known as a multifunctional inflammatory cytokine, playing a significant role in the progression of atherosclerosis, therefore it may be a critical contributor of CAD and acute MIF release and chronically elevated MIF play distinct roles in ischemic heart disease." (PMID 33850223, 2021). "MIF not only interacts with CD74, but also engages in high affinity interactions with the chemokine receptors CXCR2 and CXCR4 to drive inflammatory leukocyte recruitment processes and may mediate the inflammatory pathogenesis of experimental atherosclerosis." (PMID 22506003, 2012). "Furthermore, blockade of MIF (macrophage migration inhibitory factor) but not of canonical ligands of CXCR2 or CXCR4 in mice with advanced atherosclerosis led to plaque regression and reduced monocyte and T-cell content in plaques." (PMID 21188276, 2010). "Inhibition or lack of MIF attenuated development of septic shock, encephalitis, autoimmune encephalomyelitis, rheumatoid arthritis, colitis, concanavalin A induced liver injury, glomerulonephritis and atherosclerosis." (PMID 19558639, 2009).
atherosclerosis (continued). "Therefore, MIF impairs cognitive function by increasing endothelial dysfunction, reducing intercellular tight junctions, increasing the permeability of the BBB, promoting atherosclerosis, enhancing reactive oxygen species production, and enhancing inflammatory responses." (PMID 39247699, 2024). "In addition, CXCR4 could be involved in the development of atherosclerosis by regulating macrophage migration inhibitor (MIF) and macrophage formation, thereby affecting leukocyte recruitment and inflammatory responses, suggesting that CXCR4 may be a therapeutic target for atherosclerosis." (PMID 35607269, 2022). "However, as MIF seems to have more pro-atherosclerotic effects, CXCL12 may have a protective function, although results are still contradictory at some level and future research should further elucidate the exact role of these chemokines in atherosclerosis." (PMID 26257740, 2015). "On the other hand, macrophage migration-inhibitory factor (MIF), a non-cognate ligand of CXCR4 as well as of CXCR2 and the CD75–CD44 complex, mediates atherosclerosis in a B-cell-dependent manner." (PMID 40986007, 2025). "In the ischemic heart, MIF and MIF-2 activate protective AMPK signaling in cardiomyocytes, but the role of MIF-2 in atherosclerosis has not been studied." (PMID 40055309, 2025). "Here, the authors have designed a peptide-based ectodomain mimic of the chemokine receptor CXCR4 that selectively targets MIF but not CXCL12 and blocks experimental atherosclerosis in vivo." (PMID 33239628, 2020). "Macrophage migration inhibitory factor (MIF) is a master regulator of proinflammatory cytokines and plays pathological roles when not properly regulated in rheumatoid arthritis, lupus, atherosclerosis, asthma and cancer." (PMID 27619729, 2017). "Although recent study showed that lack of TIMP3 increases inflammation and polarizes macrophages towards a more inflammatory phenotype resulting in increased atherosclerosis 50,51, the relationship between TIMP3 and MIF did not be detected in our study." (PMID 25661015, 2015).
rheumatoid arthritis (111 papers, 2006 to 2025). A chronic, systemic autoimmune disorder characterized by inflammation in the synovial membranes and articular surfaces. "Beyond cancer, MIF has been linked to IL-17 expression in various autoimmune disorders, such as Hashimoto’s thyroiditis and rheumatoid arthritis, where Th17-mediated responses are known to drive pro-inflammatory processes." (PMID 41159021, 2025). "MIF is implicated in numerous inflammatory and autoimmune conditions, such as rheumatoid arthritis, septic shock, and inflammatory bowel disease." (PMID 41159021, 2025). "MIF has been implicated in the pathogenesis of various diseases, including infectious diseases, inflammatory diseases, immune diseases such as rheumatoid arthritis, septic shock, and cardiovascular disease." (PMID 38846956, 2024). "MIF expression has long been associated with certain diseases such as rheumatoid arthritis, asthma and cancer with increased levels found in more aggressive forms of such diseases." (PMID 38178143, 2024). "Studies have shown that high expression levels of MIF are associated with the severity of clinical phenotypes in a variety of autoimmune and inflammatory diseases such as rheumatoid arthritis, asthma, and systemic sclerosis." (PMID 38803345, 2024). "MIF encodes the macrophage migration inhibitory factor, a pro-inflammatory molecule involved in rheumatoid arthritis." (PMID 35964012, 2022). "Variants within MIF have been recently associated to rheumatoid arthritis in southern Mexican patients." (PMID 35460423, 2022). "The minor MIF ‐173 C allele or the GC genotype has also been associated with other diseases such as rheumatoid arthritis, juvenile idiopathic arthritis, systemic sclerosis, systemic lupus erythematosus, vitiligo, and sarcoidosis." (PMID 34533238, 2021). "MIF has two functional promoter polymorphisms that increase the transcription of MIF and both are associated with susceptibility to rheumatoid arthritis." (PMID 33324425, 2020). "Recently, MIF has been associated with a variety of immune-mediated diseases such as rheumatoid arthritis (RA), systemic sclerosis, and inflammatory bowel disease." (PMID 31616649, 2019). "Increased production of MIF has been linked to a more aggressive course of immunoinflammatory diseases, such as, asthma and rheumatoid arthritis." (PMID 29707160, 2018). "Clinical observations showed that increased MIF plasma levels are closely associated with myocardial infarction, critical illness, rheumatoid arthritis, or chronic kidney disease." (PMID 29728137, 2018). "In multiple rat and mouse models of rheumatoid arthritis, anti-MIF antibodies or genetic MIF deficiency is associated with significant inhibition of disease." (PMID 25821795, 2015). "Genetic studies have identified associations between MIF polymorphisms and autoimmune diseases, including rheumatoid arthritis (RA), systemic lupus erythematosus (SLE), type I diabetes, and autoimmune liver disease." (PMID 26617609, 2015). "Aberrant changes in MIF expression and function have been implicated or suggested in many inflammatory and immune response-related conditions, including rheumatoid arthritis, ankylosing spondylitis, and ocular inflammation." (PMID 24667663, 2014). "IL-7 is known to be an inflammatory mediator associated with arthritic diseases, and MIF is a proinflammatory cytokine involved in several inflammatory disorders, including rheumatoid arthritis, inflammatory bowel disease, psoriasis, and multiple sclerosis." (PMID 23533306, 2013). "Several studies have shown that the MIF genetic variants regulate the MIF serum levels in various diseases, such as; sarcoidosis, malaria, schistosomiasis, trypanosomiasis, leishmaniasis, rheumatoid arthritis, ulcerative colitis and atopy." (PMID 24066864, 2013).
rheumatoid arthritis (continued). "MIF has been implicated in the pathogenesis of multiple organ-specific autoimmune diseases including type 1 diabetes, rheumatoid arthritis, multiple sclerosis, Guillain–Barr’esyndrome, Crohn’s disease, autoimmune myocarditis, glomerulonephritis, hepatitis, thyroiditis, and psoriasis." (PMID 37616250, 2023). "Similarly, numerous studies demonstrate a role for IL-8 and MIF in propagating synovial inflammation in Rheumatoid Arthritis and MIF gene promoter polymorphisms have been shown to correlate with the 28-joint Disease Activity Score." (PMID 35052454, 2022). "In a similar way, although MIF has been implicated in the pathogenesis of both experimental and human rheumatoid arthritis (including the cognitive decline that can be observed in patients with RA), few studies have worked toward this direction of evaluation for either natural products or compounds." (PMID 33924632, 2021). "In agreement with these proinflammatory properties, preclinical and clinical studies by ourselves and others have indicated that MIF is implicated in the pathogenesis of autoimmune diseases, including rheumatoid arthritis (RA), type 1 diabetes, and multiple sclerosis and Guillain-Barré syndrome." (PMID 33401503, 2021). "MIF expression/activity in macrophages has been implicated in the pathogenesis of numerous inflammatory conditions including bacterial sepsis, rheumatoid arthritis, acute respiratory distress syndrome (ARDs), and atherosclerosis." (PMID 33324425, 2020). "Therefore, it is not surprising that MIF plays an important role in immunity and that excess MIF expression has been linked to exaggerated inflammation and immunopathology in diseases such as rheumatoid arthritis, and inflammatory bowel disease." (PMID 31497025, 2019). "Interestingly, the D-DT gene lacks the CATT5–8 microsatellite repeat, rs5844572, that controls MIF production and is associated to increased severity of rheumatoid arthritis." (PMID 29707160, 2018). "These polymorphisms in the MIF gene are also associated with several immune-mediated inflammatory diseases, including atopy, asthma, juvenile idiopathic arthritis, rheumatoid arthritis, psoriasis, and psoriatic arthritis, suggesting that the polymorphisms are functionally important." (PMID 27598332, 2016). "Similarly, MIF-794 allele 7 has been shown to be a risk factor for the development of rheumatoid arthritis; however, 794 allele 5 is correlated to reduced disease severity." (PMID 27014277, 2016). "Previous studies reported that increased MIF was associated with several diseases such as rheumatoid arthritis (RA), disseminated intravascular coagulation (DIC), acute respiratory distress syndrome (ARDS), sepsis and other critical illnesses." (PMID 33482739, 2021). "Also, the role of MIF in human disease has been recently emphasized since it has been suggested that polymorphisms modifying MIF expression could be associated with severe rheumatoid arthritis, fibrosis and asthma." (PMID 29545822, 2018). "Genetic variations in MIF have been shown to be associated with many infectious diseases, such as; sarcoidosis, malaria, schistosomiasis, trypanosomiasis, and leishmaniasis as well as inflammatory autoimmune diseases including rheumatoid arthritis, ulcerative colitis and atopy." (PMID 24066864, 2013). "The blockade of CD74 expression and its partner macrophage migration inhibitory factor has been applied as a targeted therapy for autoimmune encephalomyelitis and rheumatoid arthritis." (PMID 40761479, 2025). "Initial studies examining the role of MIF in autoimmune disease were largely focused on studying its expression in rheumatoid arthritis (RA) patients." (PMID 40092999, 2025). "Elevated levels of MIF have been detected within inflamed synovial tissue of rheumatoid arthritis patients, highlighting its involvement in localized inflammation." (PMID 41159021, 2025).